BDNF (brain derived neurotrophic factor)
Diseases named in the same sentence as BDNF in open-access papers (continued):
Sharing a sentence is not in itself a finding about the gene and the disease.
depression (continued). "In addition, in recent years, the cyclo-AMP responsive element-binding protein (CREB) cascade and its effect on the brain-derived neurotrophic factor (BDNF) have made some rationales for the pathogenesis and treatment of depression." (PMID 35979473, 2022). "It is noteworthy, however, that the way by which BDNF is involved in the reactivity to stress in animal models and in the pathogenesis of depression has not yet been precisely established." (PMID 36499323, 2022). "In addition, the levels of NAMPT, NAD, BDNF, pCREB/CREB, monoamine neurotransmitters, and CORT were changed in Namptflox/flox mice and rats with CUMS-induced depression." (PMID 36552159, 2022). "Various NTs, including BDNF, NGF, and GDNF, as well as their receptors can also be upregulated by lithium, a metal with a long-lasting history of use as first-line drug for treating bipolar disorder and depression." (PMID 35892326, 2022). "The current study reveals decreased levels of BDNF among the PSD group compared to PwS with no clinical depression." (PMID 35287688, 2022). "Our findings demonstrated that in patients with depression without any treatment, the peripheral levels of BDNF levels were significantly decreased relative to levels in nondepressed healthy controls (SMD = −0.89, 95% CI = −1.41, −0.38, p < .0001)." (PMID 35510613, 2022). "Therefore, the aim of the current study is to investigate the potential effects of combination of saffron and chamomile on depression through PHQ 9 scale and related parameters such as tryptophan, BDNF, CRP." (PMID 36217471, 2022). "Decreased levels of brain-derived neurotrophic factor (BDNF) are known to cause erratic synaptic plasticity, which can subsequently lead to depression, suggesting that CuIIa has a potential use in antidepressant diseases and as a neuroprotectant by downregulating the CaMKII-CREB-BDNF pathway." (PMID 36355498, 2022). "Since the relationship among peripheral BDNF, depression and obesity is not well-defined, the aim of the present report has been to address this issue taking advantage of the contribution played by extracellular vesicle (EV)-derived miRNAs." (PMID 35911513, 2022). "Additionally, the study suggested that augmented MBCT following pharmacotherapy elevated the serum levels of BDNF and NGF in depression patients." (PMID 35069013, 2022). "Our results showed that repeated I3C treatment selectively prevented the CSDS-induced depression- but not anxiety-like behaviors in mice, with an attenuation of neuroinflammation and oxido-nitrosative stress as well as an increase in BDNF levels in the brain." (PMID 35242039, 2022). "Neuronal cultures isolated from the hippocampus of rat models of depression show increased levels of BDNF when the rats were treated with ketamine, as opposed to those that were not." (PMID 35546951, 2022). "Several studies have confirmed that preoperative depression may contribute to the development of POCD, possibly due to hippocampal atrophy, reduced brain-derived neurotrophic factor expression, and increased production of inflammatory cytokines." (PMID 36219614, 2022). "It has been previously propounded that patients suffering from depression may have decreased levels of NGF and BDNF, and fluoxetine might increase those levels." (PMID 34991456, 2022). "In the pathophysiology of depression, their influence ranges from epigenetic mechanisms via HDAC inhibition to downregulation of pro-inflammatory cytokine production, vagus nerve stimulation, microglia maturation, and BDNF production." (PMID 35807841, 2022). "The search terms included brain‐derived neurotrophic factor or BDNF in combination with depression, without year restriction." (PMID 35510613, 2022). "The reduction of BDNF levels is not specific to depression, and similar reductions have been observed in other neuropsychiatric disorders, such as schizophrenia and dementia." (PMID 36142808, 2022).
depression (continued). "The results showed that the CREB/BDNF pathway was not significantly affected in the hippocampus of SNI rats without depression." (PMID 35401106, 2022). "These cytokines could additionally block serotonin production, decrease plasma tryptophan levels, suppress the expression of brain-derived neurotrophic factor (BDNF), and, in turn, increase the chance of depression." (PMID 35600820, 2022). "With this in mind, we speculate that acupuncture may modulate the enhanced signaling of both pCREB and BDNF levels in the brain reward circuit of MC903-induced AD mice with comorbid anxiety and depression-like behaviors." (PMID 36088447, 2022). "Therefore, H3k9bhb played a crucial role in depression and was induced by BHB and then possibly activated the BDNF gene." (PMID 36172354, 2022). "In depression, probiotic supplementation may counter inflammatory and immune-mediated signaling and HPA axis overactivation, with upregulated BDNF expression and increased production of neurotransmitters (GABA, serotonin, norepinephrine, and dopamine)." (PMID 35807931, 2022). "In our previous study, we have also concluded that BDNF is a valuable predictor of poststroke depression but not for poststroke anxiety." (PMID 35510613, 2022). "Unlike the large effect of BDNF reduction in depression, the most recent large-scale meta-analysis suggests that the effect size for BDNF decrement in MCI is small to medium." (PMID 35910248, 2022). "Another study that evaluated the effect of ketamine in individuals with depression did not observe changes in the plasma levels of BDNF or VEGF." (PMID 36559251, 2022). "Collectively, it is likely that higher expression of miR-132-5p in the PFC plays a role in depression-like phenotypes, and that blockade of miR-132-5p in the PFC could produce antidepressant-like effect through increased expression of BDNF." (PMID 36171191, 2022). "Similar to BDNF, CREB also play a critical role in the pathophysiology of depression." (PMID 35959431, 2022). "Six trials with 411 patients and 245 patients without depression compared serum BDNF between these two groups." (PMID 35287688, 2022). "A recent article has shown that the expression of BDNF at both the mRNA and protein level was up-regulated in the hippocampus by BoNT/A, and therefore the downstream ERK-CREB signaling pathway was activated in depression mice models." (PMID 36668838, 2022). "Because it is difficult to confirm a definite relationship between the peripheral level of BDNF with depression, we advocate that we should rather focus on studying mBDNF and proBDNF separately, not BDNF as a whole, in depression." (PMID 35510613, 2022). "With respect to dual diagnosis patients, BDNF levels are shown to present differences in samples from cocaine addicts with and without depression." (PMID 35370811, 2022). "This study showed that the mean adjusted serum level of BDNF l for disease severity and depression in the FM group did not significantly differ from the non-FM NP group." (PMID 35501732, 2022). "Specifically, a history of depression in drug‐naïve or drug‐free depressed patients was negatively correlated with blood BDNF levels." (PMID 35510613, 2022). "BDNF is a major neurotrophic factor that functions in the maintenance and the survival of neurons, TrkB and CREB plays a vital role in depression and antidepressant responses." (PMID 35769142, 2022). "The expression levels of miRNAs were detected by qRT-PCR, and the expression levels of Wnt2, depression-impacted proteins (GFAP, BDNF, CREB), brain neurotransmitters (5-HT, NE, DA) and apoptosis-related proteins (Bax and Bcl-2) were evaluated by qRT-PCR and western blot." (PMID 33927285, 2021).
depression (continued). "Low serum BDNF levels were observed in RA patients with depression compared to RA patients without depression." (PMID 33673283, 2021). "In this study, we found that HFD simultaneously induced the down-regulation of BDNF mRNA in hippocampus and VMH, suggesting that BDNF may play a role in depression induced by high-fat diet." (PMID 34054732, 2021). "Many studies provide evidence of the relationship between stress, depression, impaired neurogenesis in the hippocampus, and the negative feedback between BDNF and cortisol." (PMID 34300001, 2021). "Kaempferol promotes the protein expression of brain-derived neurotrophic factor (BDNF) and nerve growth factor (NGF) in hippocampal tissue from aged rats with chronic stress/depression, and these changes resulted in neuroprotection and improved depression-like behaviour." (PMID 34471414, 2021). "A significant positive correlation was found between the depression severity or omega-6/omega-3 FA ratio and plasma thromboxane B and a negative correlation with BDNF." (PMID 33801688, 2021). "The outcomes at the baseline and follow-up in both groups included blood BDNF levels, sit-to-stand test (STS), 6-minute walk test (6MWT), Fibromyalgia Impact Questionnaire (FIQ), Pittsburgh Sleep Quality Index (PSQI), Beck Depression Inventory (BDI), and visual analogue scale (VAS)." (PMID 34900203, 2021). "The antidepressant effect of ketamine is seemingly in agreement with the glutamatergic hypothesis of depression, postulating that NMDAR antagonism increases the synthesis of the brain-derived neurotrophic factor (BDNF)." (PMID 34204579, 2021). "In patients with depression the DNA methylation of BDNF and negative relationship between serum BDNF level and miR-132/miR-182 levels are observed." (PMID 34300001, 2021). "In this review article, we first provide the background of the present situation and recent research progress regarding the brain regional functions of BDNF, including the prefrontal cortex (PFC), hippocampus, and nucleus accumbens (NAc), in the pathophysiology of depression." (PMID 34577589, 2021). "Moreover, the binding of NTRK2 and BDNF activates the PIK3CA/AKT1 pathway, which promotes synaptic plasticity and enhances long-term potentiation to alleviate depression." (PMID 33935736, 2021). "Additionally, candidate gene studies discovered that BDNF and SLC6A4 hypermethylation were related to depression or major depressive disorder (MDD)." (PMID 34341332, 2021). "More important is our present finding about the involvement of PI3K/Akt/FoxO3a, GSK3β, and BDNF, is new and have not been investigated including in animal models of depression." (PMID 34721013, 2021). "We analyzed the effect of jasmine tea on the intestinal microorganisms of CUMS at the levels of BDNF, 5-HT, and GLP-1 in the hippocampus and cerebral cortex, and explored the possible mechanism by which jasmine tea ameliorates CUMS-induced depression in this study." (PMID 35010973, 2021). "Focusing the region-specific BDNF regulation by Shati/Nat8l and modulating the DRN by Shati/Nat8l-BDNF pathway, we review the application of these findings as a novel therapeutic strategy for the depression in below." (PMID 34577589, 2021). "The mechanism may be to regulate the expression of brain-derived neurotrophic factor (BDNF) by altering the expression of miR-204-5p, thereby affecting the depression-like behavior of CMS mice." (PMID 34257681, 2021). "Furthermore, ablation of Ido1 exerted stress resistance and decreased the sensitivity of depression in CUMS mice with the stable BOLD signals, BDNF expression and neurogenesis in hippocampus." (PMID 33591947, 2021). "A three way interaction between brain-derived neurotrophic factor: Met allele, biallelic 5-HTTLPR: ss-allele and no/mild childhood abuse was found to influence depression for women." (PMID 33614574, 2021).
depression (continued). "Moreover, studies on animal models showed that an increase in BDNF and NGF expression is effective in improving memory impairment and depression." (PMID 33804892, 2021). "In patients treated with antidepressants, there is an increase in the levels of BDNF mRNA and a reversion of the decrease in CREB levels seen in patients with depression, which could be mechanisms of action in mood disorders." (PMID 34295268, 2021). "Here, we examine the serum 12,13 diol/epoxide ratio and BDNF concentrations inT2DM patients with and without depression." (PMID 34612709, 2021). "To date, no study has reported on the status of BDNF in blood from paired maternal and fetal samples in relation to maternal symptoms of both depression and anxiety." (PMID 33462179, 2021). "While knocking down miR-124 improved depression-like behavior in depression rats, which might be related to the increased expression of CREB1 and BDNF in the hippocampus." (PMID 34054732, 2021). "Mice treated with LPS displayed depression-like behaviors, pronounced neuroinflammation, increased HDAC1 expression, and reduced eEF2 activity, as accompanied by altered synaptogenic factors including BDNF, SNAP25, and PSD95." (PMID 33526073, 2021). "One of the leading hypotheses is the “Neurotrophic factor hypothesis,” which explains that the decreased expression of neurotrophic factor, such as a brain-derived neurotrophic factor (BDNF), is related to the development of depression." (PMID 34393735, 2021). "DNA methylation of other BDNF regions did not have a significant effect on reward bias in the depression group (all ps > 0.05)." (PMID 34325733, 2021). "Thus, the present results demonstrate the dipeptide BDNF mimetic GSB-106 reversed depressive-like behavior and restored hippocampal neuroplasticity in a rodent depression model." (PMID 33578683, 2021). "The hippocampal BDNF expression, but not the TrkB, were significantly reduced in mTBI-J, and the mTBI-J treatment-induced depression-like behavior was lessened after four weeks of 7,8-DHF administration." (PMID 34959450, 2021). "In contrast, another study has shown, Val66Met polymorphism did not appear to affect the link between food quality and BDNF serum in terms of depression prediction." (PMID 34580389, 2021). "Such a violation of synaptic connectivity can potentially result in the decrease in neurotrophic factors such as BDNF, the overall decrease in NMDA signaling, and the inhibition of mTOR signaling that subsequently leads to the manifestation of depression-like behavior." (PMID 34064233, 2021). "Numerous studies have demonstrated that the BDNF expression level in PSD patients is lower than that without depression." (PMID 34093193, 2021). "Studying the relationship between brain-derived neurotrophic factor (BDNF) and post-stroke depression (PSD) may help determine the potential for depression in stroke patients at the earliest stage possible." (PMID 34141514, 2021). "These indirect links between motilin and BDNF require examination in human subjects with and without depression." (PMID 34575041, 2021). "In particular, these findings showed that ECS induces significant increases of BDNF levels in the rat hippocampus and that chronic ECS treatment also effectively increases hippocampal BDNF in the corticosterone animal model of depression." (PMID 34573142, 2021). "BDNF has both pro- and anti-depressant effects; therefore, the regulation of BDNF in the whole brain is not a beneficial strategy for the treatment of depression." (PMID 34577589, 2021). "In addition, recent works implicate miR-16-5p, miR-24-3p and miR-146a-5p in the regulation of MAPK downstream BDNF, IGF2 and WNT signaling in depression." (PMID 33546327, 2021). "Considering the strong region-specific contribution of BDNF to depression pathogenesis, the regulation of BDNF in the whole brain is not a beneficial strategy for the treatment of depression." (PMID 34577589, 2021).
depression (continued). "In depression, EA exerts effects on neuropeptides and neurotransmitters; proinflammatory cytokines; serum copper, zinc, calcium and magnesium levels; the HPA axis; BDNF; signaling pathways; the genome; and hippocampal synaptic plasticity." (PMID 33436036, 2021). "Downregulation of miR-383 significantly inhibited the apoptosis and inflammatory response of hippocampal neurons, and increased the expression levels of GFAP, BDNF and CREB which were impacted in depression, as well as neurotransmitters, then attenuated neural injury in rats induced by CUMS." (PMID 33927285, 2021). "In a chronic stress-induced depression model in mice, the levels of salt-inducible kinase 2, which is a kinase of CRTC1, was increased in the hippocampus, resulting in inhibition of CRTC1/CREB-regulated BDNF expression." (PMID 34977362, 2021). "However, recently Troyan and Levada showed that patients diagnosed with depressive disorders had higher levels of IGF-1, but lower levels of brain-derived neurotrophic factor (BDNF)." (PMID 34574400, 2021). "Thus, IDO1 hyperactivity played crucial roles in modulating 5-HT metabolism and BDNF function thereby impacting outcomes of hippocampal neurogenesis and BOLD signals in depressive disorder." (PMID 33591947, 2021). "Human studies show that brain-derived mature neurotrophic factor (BDNF) (but not its precursor proBDNF) is reduced in patients with depressive disorders." (PMID 33804468, 2021). "REST can also repress expression by binding to RE1 sites, which can be found on the regulatory elements of the corticotropin-releasing hormone gene, CRH and brain-derived neurotrophic factor (BDNF) genes, among others; both genes are important in stress and depression." (PMID 31740756, 2020). "Finally, the cAMP signaling pathway was verified as the mechanism of GH against depression through experimental validation of the target proteins (cAMP, PKA, p-CREB, and BDNF)." (PMID 33658934, 2020). "NK109 significantly alleviated Escherichia coli K1-induced cognitive impairment- and depression-like behaviors in germ-free and SPF mice by regulating the immune response through NF-κB-involved BDNF expression, IL-1β expression, and vagus nerve-mediated gut–brain signaling." (PMID 33182607, 2020). "YL did not affect hippocampal mRNA and protein expression of BDNF, which is a regulatory factor of both neurogenesis and depression-like behavior." (PMID 32042019, 2020). "In line with this, a systematic review and meta-analysis reported reduced serum BDNF levels in PD patients compared to healthy controls in spite of the presence of co-morbidities such depression among non-depressed and depressed PD patients." (PMID 33584215, 2020). "It has previously been shown that BDNF levels are indeed decreased in patients with major depressive disorder, but not in patients with dysthymia." (PMID 32372985, 2020). "A meta-analysis showed that there were small increases in peripheral BDNF levels after pharmacological treatment for manic episodes, and no significant changes before and after treatment for depressive episodes." (PMID 33061913, 2020). "However, in a genetic animal model of depression, though brain BDNF increased instantly after ECS was applied, it normalized after repeated BDNF." (PMID 32153449, 2020). "Elevated BDNF expression in the hippocampus was also detected in this prevention, which suggests a negative relationship between stress-related depression and hippocampal BDNF levels." (PMID 32085670, 2020). "At present, the brain-derived neurotrophic factor (BDNF) and neurogenesis hypotheses have highlighted the important role of plasticity in depression." (PMID 33293948, 2020). "Besides this, flavonoids are also believed to boost the levels of brain-derived neurotrophic factor (BDNF), an important biomarker of depression, found in the hippocampus; BDNF is a neurotrophin that is known to help in neuronal survival and protection." (PMID 33521033, 2020).